TRPM4 (transient receptor potential cation channel subfamily M member 4)
Diseases named in the same sentence as TRPM4 in open-access papers (continued):
Sharing a sentence is not in itself a finding about the gene and the disease.
aortic stenosis (2 papers, 2022 to 2025). Aortic valve stenosis is a aortic valve disease caused by the incomplete opening of the aortic valve. "Indeed, wild‐type mice developed aortic stenosis associated with fibrosis 5 months after valve irradiation, which was less prominent in mice with Trpm4 gene disruption (Trpm4−/−)." (PMID 40194969, 2025). "The TRPM4 channel therefore appears as a participant in the process linking irradiation to aortic stenosis." (PMID 36139640, 2022). "It shows that, even if the road is still long for a therapeutic treatment of aortic stenosis based on the modulation of TRPM4, this approach could be considered." (PMID 40194969, 2025). "Finally, TRPM4 was recently shown to be overexpressed at the protein level in aortic valves from patients suffering from aortic stenosis." (PMID 36139640, 2022). "TRPM4 is thus a candidate to participate in VIC osteogenic differentiation, leading to aortic stenosis." (PMID 40194969, 2025). "Regarding the relation of TRPM4 to aortic stenosis in human, it was observed an enhanced TRPM4 protein expression in calcified compared with noncalcified valves." (PMID 40194969, 2025).
aortic valve stenosis (2 papers, 2022 to 2023). Aortic valve stenosis (AVS) is a condition characterized by narrowing of the heart's aortic valve opening. "Using a model of targeted aortic valve irradiation in mice, we observed the development of aortic valve stenosis associated with fibrosis 5 months after irradiation treatments which was prevented in transgenic mice lacking TRPM4 expression." (PMID 36139640, 2022). "The TRPM4 cation channel is known to participate in cellular remodeling including the transition of cardiac fibroblasts to myofibroblasts, similar to that observed during aortic valve stenosis." (PMID 36139640, 2022). "The monovalent non-selective cation channel TRPM4 is known to be involved in calcium handling and to participate in fibroblast transition to myofibroblasts, a phenomenon observed during aortic valve stenosis." (PMID 36139640, 2022). "TRPM4 is a monovalent non-selective cation channel involved in calcium handling and participating in fibroblast transition to myofibroblasts, a phenomenon observed during aortic valve stenosis." (PMID 37762794, 2023).
atherosclerosis (2 papers, 2024 to 2025). A disease characterized by the build-up of fatty material and calcium deposition in the arterial wall resulting in partial or complete occlusion of the arterial lumen. "Despite this, the specific role and mechanisms of TRPM4 in atherosclerosis have not been fully understood." (PMID 38269270, 2024). "TRPM4 knockdown substantially reduced cellular inflammation, oxidative stress, and lipid peroxidation, thereby improving endothelial function and potentially modulating atherosclerosis progression." (PMID 40308274, 2025).
brain infarct (2 papers, 2019 to 2024). "Accordingly, the brain infarct volume and recovery of motor function were enhanced by genetic deletion of TRPM4, although the protective effect of TRPM4 silencing on motor function was only transient and ceased at day 5 post-intervention." (PMID 32038296, 2019).
breast invasive carcinoma (2 papers, 2020 to 2022). "This suggests a progressive pattern of TRPM4 expression upregulation from normal into pre-cancerous DCIS, and its expression might be maintained in DCIS that develops into invasive breast carcinoma." (PMID 32484822, 2020).
cervical (2 papers, 2015 to 2018). "Finally, human cervical-uterine tumor samples and cervical-uterine cancer derived cell lines display a high TRPM4 mRNA level and an amplification of TRPM4 channel." (PMID 29875336, 2018).
complete heart block (2 papers, 2018 to 2025). "In the present study, we identified four novel TRPM4 genetic variants found in patients with either complete heart block (CHB) or idiopathic ventricular fibrillation (IVF)." (PMID 29568272, 2018).
Fallot tetralogy (2 papers, 2020 to 2021). "In human cardiac tissue, TRPM4 protein expression was described in the conductive system, in the atrial muscle, and in cardiac samples of 5-month-old Fallot tetralogy patients." (PMID 34502410, 2021). "We also report novel plausible gene–disease associations for tetralogy of Fallot/pulmonary stenosis (CDC42BPA, FGD5), hypoplastic left or right heart (SMARCC1, TLN2, TRPM4, VASP), congenitally corrected transposition of the great arteries (UBXN10), and early-onset cardiomyopathy (TPCN1)." (PMID 32037394, 2020).
glaucoma (2 papers, 2018 to 2025). Increased pressure in the eyeball due to obstruction of the outflow of aqueous humor. "TRPM4 was found to be expressed in astrocytes and to be involved in astrocyte swelling in several pathological conditions, such as brain edema, and glaucoma." (PMID 29996905, 2018).
HIV-1 infection (2 papers, 2020 to 2023). The type species of lentivirus and the etiologic agent of acquired immunodeficiency syndrome (AIDS). "HIV-1 infection increases expression of inflammatory markers (TLR4, TNF-α, and NF-κB) and upregulates Sur1 and Trpm4 in astrocytes of Tg26 mouse brain tissues." (PMID 33293383, 2020).
Huntington disease (2 papers, 2025). Huntington disease (HD) is a rare neurodegenerative disorder of the central nervous system characterized by unwanted choreatic movements, behavioral and psychiatric disturbances and dementia. "In a Huntington’s disease (HD) mouse model, treatment with memantine or targeting the NMDAR/TRPM4 complex with FP802 restored gene expression, notably Inhba, Homer1 and Bdnf, and attenuated the decrease of the HD disease marker Ppp1r1b (DARPP-32)." (PMID 41339520, 2025).
injury (2 papers, 2019 to 2022). Damage inflicted on the body as the direct or indirect result of an external force, with or without disruption of structural continuity. "Although pharmacological inhibitors of TRPM4 have several issues, FFA appears to represent a multipotent and promising agent in the management of post-CA brain injury." (PMID 36050694, 2022). "TRPM4, which can lead to catastrophic BBB disruption and a persistent neuroinflammatory response, could represent a promising and clinically relevant target for the future treatment of post-CA induced brain injury." (PMID 36050694, 2022).
intracranial hypertension (2 papers, 2020 to 2021). A finding characterized by increased cerebrospinal fluid pressure within the skull. "Two TRPM4 SNPs were associated with intracranial hypertension after TBI: rs8104571 and rs150391806." (PMID 31936452, 2020). "Interestingly, significant interactions between ABCC8 and TRPM4 single nucleotide polymorphisms (SNPs) have also been reported, where certain genotype combinations containing risk alleles in both genes markedly and consistently increase the odds of several measures of intracranial hypertension." (PMID 34769328, 2021). "They support the theory that ABCC8 and TRPM4 genetic variation may play a role in cerebral edema development, intracranial hypertension and outcome after TBI." (PMID 31936452, 2020).
leukaemia (2 papers, 2021 to 2022). "In this regard, integrated methylome, transcriptome, and epigenetic analysis showed that the expression level of many genes is dysregulated in paediatric leukaemia, and among them, the presence of TRPC1, TRPC4, TRPC3, TRPM2, TRPM4, and TRPM8 also stands out." (PMID 34065398, 2021).
memory impairment (2 papers, 2023 to 2025). "To investigate the role of TRPM4 in memory impairment often seen in chronically epileptic mice, we performed object location memory (OLM) and novel object recognition (NOR) tests on control (saline injected) and epileptic mice on both genotypes." (PMID 37101159, 2023).
overactive bladder (2 papers, 2021 to 2024). Symptom of overactive detrusor muscle of the urinary bladder that contracts with abnormally high frequency and urgency. "TRPM4 function in the smooth muscle of the urinary bladder made TRPM4 a potential target of overactive bladders." (PMID 35056097, 2021). "Experimental studies have demonstrated transient increases in intracellular calcium, such as calcium sparks, puffs, and waves, which could activate TRPM4 channels locally, exacerbating overactive bladder symptoms." (PMID 38999984, 2024). "This suggests that overexpression of TRPM4 channels across the DSM cell membrane could induce heightened spontaneous contractions, a primary symptom of overactive bladder." (PMID 38999984, 2024). "In conclusion, TRPM4 channels are pivotal in regulating human DSM function, and TRPM4 channel inhibitors could be promising targets for treating overactive bladder." (PMID 38999984, 2024).
progressive cardiac conduction defects (2 papers, 2011 to 2019). "First, a linkage study in a large South African pedigree with an autosomal-dominant form of progressive familial heart block type 1 (PFHBI) revealed a susceptibility locus on 19q13.33, a region which contains the TRPM4 gene." (PMID 31316392, 2019).
respiratory failure (2 papers, 2019 to 2021). The significant impairment of gas exchange within the lungs resulting in hypoxia, hypercarbia, or both, to the extent that organ tissue perfusion is severely compromised. "Some of these results were confirmed in adult mice using TRPM4-targeted short hairpin RNA, where TRPM4 suppression decreased the tidal volume but increased respiratory frequency, often followed by gasping and fatal respiratory failure." (PMID 35056097, 2021). "Adult mice transduced with Trpm4-targeted short hairpin RNA (shRNA) progressively decreased the tidal volume of breaths yet surprisingly increased breathing frequency, often followed by gasping and fatal respiratory failure." (PMID 30789900, 2019).
triple-negative breast carcinoma (2 papers, 2020 to 2025). An invasive breast carcinoma which is negative for expression of estrogen receptor (ER), progesterone receptor (PR), and human epidermal growth factor receptor 2 (HER2). "Their activity may be predicted by TRPM4 but with more accuracy adding other genes in multivariate analysis for triple negative breast cancer (TNBC)." (PMID 39932272, 2025). "Higher TRPM4 expression showed a non-significant trend for non-triple negative breast cancer (TNBC) subtypes including luminal A, luminal B and HER2-enriched (p = 0.060)." (PMID 32484822, 2020).
uterine cancer (2 papers, 2015 to 2018). Primary or metastatic malignant neoplasm involving the uterine corpus and/or the cervix. "Thus, TRPM4 channels enhance the proliferation of T-REx 293 and HeLa cervical-uterine cancer cells by promoting nucleus stability and the function of catenin as a transcriptional co-factor." (PMID 29875336, 2018).
uveal melanoma (2 papers, 2022 to 2023). A melanoma derived from melanocytes of the uveal tract. "High expression of TRPM4 predicted worse overall survival in lower-grade glioma (LGG), uveal melanoma (UVM), kidney renal clear cell carcinoma (KIRC), pancreatic adenocarcinoma (PAAD), mesothelioma (MESO), and thyroid carcinoma (THCA)." (PMID 35493463, 2022). "In the Cancer Genome Atlas database, TRPM4 and TRPV2 were identified as negative prognostic markers in uveal melanoma." (PMID 37240443, 2023).
allergic contact dermatitis (1 paper, 2022). An inflammatory skin condition caused by an immune response to direct contact between the skin and an allergen. "We next asked if TRPM4 GoF mice have susceptibility to other stimuli using two other dermatitis models, i.e., croton oil-induced irritant contact dermatitis and di-nitro-fluoro-benzene (DNFB)-induced allergic contact dermatitis." (PMID 36341417, 2022).
anaphylaxis (1 paper, 2016). An acute hypersensitivity reaction that occurs from exposure to an allergen. "Lack of this regulatory mechanism might be responsible for the accelerated anaphylactic response in a passive cutaneous anaphylaxis test in TRPM4 deficient mice." (PMID 27624684, 2016).
Andersen syndrome (1 paper, 2017). "TRPM4 enlarges the subgroup of LQT genes (KCNJ2 in Andersen syndrome and CACNA1C in Timothy syndrome) known to increase the QT interval through a more complex pleiotropic effect than merely action potential alteration." (PMID 28315637, 2017).
asthma (1 paper, 2023). "Genes encoding mela-statin TRP channels, such as TRPM4, are involved in developing some asthma phenotypes and exacerbating asthma." (PMID 38203236, 2023).
benign prostatic hyperplasia (1 paper, 2015). A non-cancerous nodular enlargement of the prostate gland. "Areas identified as non-malignant (bottom right) or benign prostatic hyperplasia (BPH) showed no or faint TRPM4 immunoreactivity." (PMID 26496025, 2015).
bladder cancer (1 paper, 2026). "By integrating single-cell and whole-genome transcriptomic data, this study revealed significant transient receptor potential cation channel subfamily M member 4 (TRPM4) overexpression in bladder cancer (BLCA) (p < 0.05), particularly in epithelial cells." (PMID 42052292, 2026). "Bladder cancer (BLCA) is a common malignancy of the urinary system, yet the therapeutic relevance of transient receptor potential cation channel subfamily M member 4 (TRPM4) remains unclear." (PMID 42052292, 2026).
breast tumors (1 paper, 2021). "Future studies including in vivo experiments will clarify the role of TRPM4 in cancer, will elucidate the regulatory mechanisms it employs to sustain CSCs and will evaluate its potential as a therapeutic target in breast tumors." (PMID 34680485, 2021). "We found that TRPM4 was overexpressed in aggressive breast tumors in two separate patient data sets." (PMID 34680485, 2021).
cardiac arrest (1 paper, 2021). Cessation of breathing and/or cardiac function. "In a 7 min murine model of asystolic cardiac arrest from KCl injection, Abcc8 and Trpm4 mRNA levels were significantly upregulated at 6 h post-cardiopulmonary resuscitation; Trpm4 levels remained elevated at 24 h." (PMID 34769328, 2021). "After 8 min asphyxial cardiac arrest, both Abcc8 and Trpm4 mRNA, as well as SUR1-TRPM4 protein (western blot), were upregulated in the cortex and hippocampus at 24 h after injury." (PMID 34769328, 2021). "In a 10 min rat model of asphyxial cardiac arrest, both Abcc8 and Trpm4 mRNA, as well as SUR1-TRPM4 protein (by western blot and immunohistochemistry), were upregulated at 6 h and peaked at 24 h." (PMID 34769328, 2021).
cervical adenocarcinoma (1 paper, 2022). An adenocarcinoma arising from the cervical epithelium. "Interestingly, TRPM4 showed higher expression only in cervical adenocarcinoma; while TRPV3 showed lower expression only in cervical adenocarcinoma." (PMID 36072430, 2022).
clear cell renal cell carcinoma (1 paper, 2025). "In this study, we comprehensively characterized the expression profile of TRPM4 across multiple tumor types through systematic bioinformatics analysis, with a particular focus on evaluating its clinical relevance and prognostic value in clear cell renal cell carcinoma (KIRC)." (PMID 41584840, 2025). "Second, while in vitro functional assays clearly demonstrated a tumor-suppressive role for TRPM4 in clear cell renal cell carcinoma, in vivo validation was not included in the current study." (PMID 41584840, 2025).
colorectal adenocarcinoma (1 paper, 2022). The most common type of colorectal carcinoma. "To study the effect of CYBA and TRPM4 on cell proliferation, we knocked down CYBA and TRPM4 with respective siRNAs, separately, in two colorectal adenocarcinoma cell lines, LS174T and HT-29; LS174T is a mucin secreting cell line." (PMID 35158942, 2022).
congenital heart block (1 paper, 2015). Heart block that occurs on or before 28 days of life. "Out of the two patients with congenital heart block in the absence of congenital heart disease, one was genotype positive for the LDB3 and TRPM4 variants (patient 4) and the other one was negative." (PMID 26636822, 2015).
Fibroadenoma (1 paper, 2020). A benign tumor of the breast characterized by the presence of stromal and epithelial elements. "In addition, three cases in the TMA series were fibroadenomas where one of the cases was positive for TRPM4 (frequency: 50%; intensity: weak)." (PMID 32484822, 2020).
hematoma (1 paper, 2024). A hematoma is a collection of blood from a vascular structure into an extravascular space. "Activation of both KATP channels and TRPM4 channels contributes to enhanced activity of monocytes/macrophages, so it is possible that diazoxide mitigates extravascular blood by promoting hematoma absorption." (PMID 39148545, 2024).
hyperreactivity (1 paper, 2023). "TRPM4 is associated with cold airway hyperreactivity, TMEM102 and CD200R1 are involved in Th cell activation, and ST3GAL3 and B3GNT7 are associated with protecting the distal airways against destruction." (PMID 38203236, 2023).
hypertrophic cardiomyopathy (1 paper, 2017). A condition in which the myocardium is hypertrophied without an obvious cause. "At least, it can be stated that none of the five TRPM4 variant carriers fulfilled the echographic criteria for hypertrophic cardiomyopathy." (PMID 28315637, 2017).
inflammatory skin disease (1 paper, 2022). Inflammatory skin disorders covers a broad category that includes many conditions ranging in severity, from mild itching to grave medical health complications These disorders are common in people of all ages and races. "Therefore, we hypothesized TRPM4 was involved in not only PSEK but could potentially play a regulatory role in other inflammatory skin diseases." (PMID 36341417, 2022).
ischemic heart disease (1 paper, 2015). "Thus, the injection of TRPM4 blocker before myocardial reperfusion may constitute a new strategy to mitigate I/R injury in patients with ischemic heart disease." (PMID 25836769, 2015).
liver cancer (1 paper, 2021). An epithelial or non-epithelial malignant neoplasm that arises from the liver. "However, to date, the putative role of TRPM4 in liver cancer pathophysiology has not been investigated." (PMID 33562811, 2021).
metastatic cancer (1 paper, 2019). A carcinoma which has spread from the original site of growth to another anatomic site. "Compared to CRC cells representing early cancer stages, TRPM4 protein expression was the highest in cells representing late‐stage metastatic cancer." (PMID 31441200, 2019).
Myocardial fibrosis (1 paper, 2025). "Consistently, pre-treatment with TGFβ1 increased the protein levels of TRPM4 and TRPM4 currents in healthy cardiac fibroblasts, thereby confirming that TRPM4 may play a crucial role in myocardial fibrosis." (PMID 40149710, 2025). "TRPM2, TRPM4 and TRPM7 emerged as the sole TRPM isoforms involved in myocardial fibrosis." (PMID 40149710, 2025).
neuropathy (1 paper, 2025). A disorder affecting the nervous system that manifests with pain, tingling, numbness, and/or muscle weakness. "TRPM4 is known to be involved in neuropathy, cardiac rhythmopathies, and tumor-related diseases by disrupting mitochondrial homeostasis 15, 29; however, its role in AP has not been reported." (PMID 40585980, 2025).
nonalcoholic fatty liver disease (1 paper, 2021). "Therefore, in the future, the regulatory mechanisms operating between nonalcoholic fatty liver disease (NAFL) and nonalcoholic steatohepatitis (NASH) and TRPM4 should be comprehensively explored to gain a complete understanding of NAFLD pathophysiology." (PMID 34887931, 2021).
ovarian carcinoma (1 paper, 2026). A malignant neoplasm originating from the surface ovarian epithelium. "For example, TrpV4, TrpC7, and several TrpM family members (TrpM2, TrpM4, TrpM8) are upregulated in ovarian cancer, where their expression negatively correlates with patient prognosis." (PMID 41557739, 2026).
polyp (1 paper, 2025). A usually exophytic mass attached to the underlying tissue by a broad base or a thin stalk. "Conversely, we observed that TRPM4 was significantly downregulated in cancer tissues compared to normal mucosa and polyp tissues." (PMID 40313460, 2025).